TTC31 (tetratricopeptide repeat domain 31)
Synonyms: FLJ12788
Tractability: PROTAC: ubiquitination databases record sites on it.
Gene: Protein-coding gene on chromosome 2 (74,483,061 to 74,494,999, forward strand). Ensembl gene ENSG00000115282.
Subcellular location (Human Protein Atlas): Cytosol; Nucleoplasm
Genetic constraint (gnomAD): Loss-of-function variants: 61 observed, 62.65 expected, observed/expected ratio (o/e) 0.97, 90% interval 0.79 to 1.21. The upper end of that interval is the gene's LOEUF score, 1.21, which puts it in group 5 of 6, group 1 being the genes least tolerant of losing a copy. Missense variants: 671 observed, 666.3 expected, observed/expected ratio (o/e) 1.01, 90% interval 0.94 to 1.07. Synonymous variants: 225 observed, 257.57 expected, observed/expected ratio (o/e) 0.87, 90% interval 0.78 to 0.98.
Homologues: Orthologues: chimpanzee TTC31 (99% identical), macaque TTC31 (83% identical), guinea pig TTC31 (75% identical), dog TTC31 (74% identical), pig TTC31 (70% identical), zebrafish si:dkey-33c12.4 (25% identical), Caenorhabditis elegans unc-45 (7% identical), Drosophila melanogaster unc-45 (7% identical). Paralogues in human: RPAP3 (13% identical), SPAG1 (12% identical), ST13 (11% identical), SGTA (10% identical), STIP1 (10% identical), UNC45B (10% identical), TTC4 (9% identical), UNC45A (9% identical), SPATA16 (9% identical), TTC12 (9% identical), SGTB (9% identical), TTC1 (8% identical), and 6 more.
Diseases named in the same sentence as TTC31 in open-access papers:
TTC31 is named in the same sentence as 2 diseases in open-access papers, as found by Europe PMC text mining. Sharing a sentence is not in itself a finding about the gene and the disease. The quoted sentences say what the papers report.
pan (1 paper, 2023). "In pan cancer, NXF2B, MSLNL, PCGF1, INO80B-WBP1, LBX2-AS1, MRPL53, LBX2, TTC31, WDR54 and WBP1 were co-altered in the TLX2-altered group." (PMID 37758722, 2023).
TTC31 also shares sentences with these, for which no sentence is quoted: cancer (1 paper).